ENSG00000275630 (novel transcript)
Gene: Long non-coding RNA gene on chromosome 14 (70,821,715 to 70,824,437, forward strand). Ensembl gene ENSG00000275630.
Gene Ontology:
Biological process: SRP-dependent cotranslational protein targeting to membrane, signal sequence recognition
Cellular component: signal recognition particle, endoplasmic reticulum targeting